IGF1 (insulin like growth factor 1)
Diseases named in the same sentence as IGF1 in open-access papers (continued):
Sharing a sentence is not in itself a finding about the gene and the disease.
cancer (continued). "In terms of the crosstalk between TAMs and cancer cells, several reports indicate the capability of TAMs to secrete IGF1 and IGF2, similarly to CAFs." (PMID 38892104, 2024). "The relationship between GH excess and IGF1 and the onset of cancer has always attracted much interest, although it is difficult to demonstrate a clear cause and effect." (PMID 38214852, 2024). "Nonetheless, the ketogenic diet has been shown to limit cancer growth in many preclinical models via lowering of insulin and IGF-1, and intriguingly has shown synergy in combination with cancer therapies that disrupt the insulin/IGF-1/PI3K axis in host organs." (PMID 38873602, 2024). "Overall, the IGF-1 system’s intricate involvement in cellular proliferation, survival, and resistance mechanisms highlights its importance in cancer biology and underscores the need for continued research to develop targeted therapies for BC treatment." (PMID 39273251, 2024). "Collectively, these pre-clinical and clinical results strongly support the development of therapeutic strategies targeting the IGF1/IGF1R axis to boost anti-cancer immunity and to potentially improve the efficacy of current immuno-oncotherapeutic approaches." (PMID 38420122, 2024). "It promotes the expression of oncogenic proteins that enhance cancer cell growth, survival, and progression such as cyclin D1, c-Myc, and insulin-like growth factor 1, while inhibiting cell cycle arrest proteins such as p21." (PMID 39742369, 2024). "IGF-1 has been demonstrated to activate the mTORC1 signaling pathway, which plays a crucial role in cancer cell proliferation and tumor progression." (PMID 38342894, 2024). "Previous studies have documented the involvement of the IGF-1/IGF-1R signaling pathway in regulating cancer stem cells across various tumors, sustaining stem cell-like properties, and fostering drug resistance." (PMID 38413558, 2024). "We validated that IGF-1 enhanced the proliferative ability of tumor cells, elevated the protein and mRNA expression of cancer stem cell markers CD133 and CD44, along with enhanced tolerance to cisplatinoid drugs and in vitro sphere formation ability." (PMID 38413558, 2024). "It has been discovered that Daf-16/FOXO-regulated genes that affect the insulin/IGF-1 pathway as influencing the formation of C. elegans cancer formation." (PMID 39558974, 2024). "In the nearest perspective, identifying candidate therapeutic targets for various IGF-1 isoforms, including Eb peptide analogues with anti-cancer activities, holds promise." (PMID 39273251, 2024). "The IGF-1 signaling pathway is frequently activated in cancer cells, and it shifts metabolic resources toward growth and proliferation." (PMID 38462638, 2024). "Metformin also modulates the insulin/IGF-1 signaling pathway, which is frequently overactive in cancer cells, lowering insulin and IGF-1 levels and thereby reducing PI3K/AKT/mTOR pathway activation, which decreases cell growth and induces apoptosis." (PMID 39272875, 2024). "This activation promotes cellular proliferation, motility, and resistance to apoptosis, making the IGF-1 system a significant factor in cancer biology." (PMID 39273251, 2024). "IGF1 stimulation also induces a transcriptional program, which influences mitochondrial biogenesis and facilitates cancer progression." (PMID 38892104, 2024). "Since IGF-1R activation relies on ligand binding and elevated IGF-1 levels promote tumor growth in BC, reducing IGF-1 levels is considered a viable anti-cancer strategy." (PMID 39273251, 2024). "Elevated levels of insulin and IGF-1 contribute to the accelerated growth of colon cells, potentially leading to cancer development." (PMID 39201651, 2024). "We have found that VCAN and IGF1 in peritumoral AT correlated with cancer Ki67 and OCT4, respectively, thereby providing an index of cancer proliferation and aggressiveness." (PMID 39501160, 2024).
cancer (continued). "IGF-1 is thought to promote cancer development by stimulating cell proliferation and inhibiting apoptosis." (PMID 37455285, 2023). "–Reduction of IGF‐1 levels mediates differential protection between normal and cancer cells in response to fasting." (PMID 36994237, 2023). "IGF-1/IGF-1R is a candidate autocrine/paracrine ligand-receptor pair that promotes cancer progenitor cell and mature cancer cell resistance to castration." (PMID 36831629, 2023). "One feature of cancer metabolism is an increase in glucose uptake, which leads to elevated insulin levels, which in turn elevates the insulin-like growth factor 1 (IGF1)." (PMID 36835094, 2023). "Radiotherapy to CAFs induced insulin-like growth factor-1 (IGF1) and stimulated survival of cancer cells, which was restrained by IGF1 receptor (IGF1R) neutralization." (PMID 37784036, 2023). "Collectively, the results in present study strongly suggest that monensin is probably to exert anti-cancer activity by inhibiting the IGF1R signaling pathway via IGF1 increase." (PMID 36896461, 2023). "The educated fibroblasts are cytocidal to CD8+ T-cells, activate cancer cell IGF-1 production, and continue to educate other NFs, in turn." (PMID 37046676, 2023). "In PCa, IGF-1 is synthesized and secreted from both cancer cells and the local niche and functions in an autocrine or paracrine manner." (PMID 36831629, 2023). "Accordingly, an important approach in cancer therapy participates in the inhibition of the IGF1 pathway." (PMID 36900213, 2023). "On the other hand, IGF-1/IGF-1R signaling has been recognized as playing a role in the development of cancer." (PMID 36891560, 2023). "IGF-1/IGF-1R signaling affects diverse biological processes in cancer cells, including promoting survival and renewal, inducing migration and spread, and promoting resistance to radiation and castration." (PMID 36831629, 2023). "Of note, IGF2 is approximately five-fold more abundant than IGF1 in serum and is often more expressed than IGF1 in cancer, in both an autocrine and paracrine manner." (PMID 36672737, 2023). "In our study, silencing of COL6 in GBM cells induced the downregulation of genes associated with cancer-relevant pathways, including PI3K/AKT, IGF1, FLT3, PDGF, and MAPK pathways." (PMID 37505240, 2023). "The insulin like growth factor 1 can increase E cadherin-mediated intercellular adhesion and promote cancer cell aggregation and entry into blood vessels." (PMID 37143649, 2023). "In prolactinomas and growing prolactinomas, PADI2 and PADI4 can promote the upregulation of the HMGA1, N-MYC and IGF-1 oncogenes by catalyzing the citrullination of histones, thus promoting the proliferation of cancer cells." (PMID 37020554, 2023). "The reduced IGF-1 levels by IF resulted in a reduction in tumor growth and progression because the cancer cells used the IGF-1 signaling pathway to convert their metabolic resources toward proliferation and growth." (PMID 38202341, 2023). "IGF-1 induces phosphorylation and internalization of its receptor and thereby induces multiple biological changes that facilitate tumorigenesis, cancer progression, metastatic spread, and even treatment resistance." (PMID 36831629, 2023). "IGF-1/IGF-1R signaling has been widely examined for its role in cancer progression through the regulation of cancer-stemness markers as well as EMT markers." (PMID 36765890, 2023). "Single SNPs in IGF-1 have been associated with increased circulating levels of IGF-1 and/or cancer risk." (PMID 38137390, 2023). "In the microenvironment, it was reported that the major sources of HGF, amphiregulin, IGF‐1, and FGF‐2 are fibroblasts, leukocyte populations, cancer‐associated fibroblasts, and epithelial/endothelial cells, respectively." (PMID 36416133, 2023). "TROP-2 signaling is involved in cancer growth, invasion, and metastasis via interaction with several ligands, including claudin-1, claudin-7, cyclin D1, and potentially IGF-1." (PMID 37237509, 2023).
cancer (continued). "IGF1 signaling is a crucial cancer-promoting pathway that controls cancer development and progression." (PMID 36774408, 2023). "Activation of the mTOR pathway through insulin-like growth factor-1 (IGF1) is also reduced in tumor-bearing mice with cancer cachexia." (PMID 37217930, 2023). "Taken together, these cohort studies strongly implicate a mechanistic role of the IGF-1 axis in cancer development, supporting targeted prevention strategies designed to blunt IGF-1 axis expression." (PMID 36331687, 2023). "The IGF1/AKT pathway is an oncogenic signaling pathway that is involved in promoting stemness in certain cancer types." (PMID 36674525, 2023). "Examination of prospective correlations of serum IGF1 with mortality, vascular disease, dementia, osteoporosis, diabetes and cancer, led to the identification of two general patterns." (PMID 37941907, 2023). "The CA repeat polymorphism is located in the promoter region of the IGF-1 gene, and it was found to be significantly associated with higher IGF-1 levels in circulation and worse cancer-specific survival in PCa." (PMID 36831629, 2023). "It was inconsistently reported that high IGF-1 and IGFBP-2 and low IGFBP-3 circulating levels are associated with high cancer risk, poor prognosis, and tumor metastasis in several cancers." (PMID 38137390, 2023). "The autocrine-paracrine growth factor, insulin-like growth factor 1 (IGF-1), has been reported to be a promoter of cancer that inhibits the sex hormone-binding globulin (SHBG) and exists in elevated levels in African American individuals." (PMID 37345032, 2023). "Enrichment analysis disclosed downregulated genes as significantly involved in several cancer associated intracellular pathways including PI3K/AKT, IGF1, FLT3, PDGF, and MAPK, together with microenvironmental processes such as ECM and TIE2 signaling." (PMID 37505240, 2023). "A natural analogue of pterostilbene, resveratrol was reported to exert its maximum effect to reduce the levels of the cancer biomarker of plasma insulin-like growth factor-1 (IGF-1) at the optimal dose of 1 g/day administered orally to healthy volunteers." (PMID 37298657, 2023). "Concomitantly, the anabolic insulin-like growth factor-1 (IGF-1) is decreased in both cancer patients and mouse models." (PMID 37240117, 2023). "Given that the growth and proliferation of various cancer cells can be promoted by IGF-1, the feasibility of using IGF-1 as a marker of the prognosis of PCa was determined." (PMID 36831629, 2023). "In IPA analysis, the top five enriched pathways included IL-15 production, circadian rhythm, Granzyme B Signaling, PD-1, PD-L1 cancer immunotherapy pathway and IGF-1 signaling." (PMID 38082307, 2023). "Cancer, which is generally positively correlated with IGF1 levels, should be regarded as an exception to this U-shaped pattern." (PMID 37941907, 2023). "Concerning the mechanisms whereby the fasting-induced reduction in insulin, IGF1 and leptin mediates cancer cell sensitization to CBIs, we first focused on the expression of enzymes from the cholesterol biosynthesis pathway." (PMID 37907500, 2023). "Surgery-induced upregulation of IGF-1 can further increase inflammation, potentially accounting for the high levels of inflammatory markers seen in this cancer subtype." (PMID 38067195, 2023). "Nutritional aspects are also important in cancer post-treatment follow-up, by the modulation of hormonal levels related to cancer progression such as hyperglycemia, abdominal fat, and IGF-1." (PMID 36814313, 2023). "Insulin has been shown to stimulate cancer cells, reduce apoptosis, and can increase carcinogenesis through IGF-1." (PMID 37069525, 2023). "Our data indicate that fasting enhances the ability of CBIs to lower cholesterol in cancer cells and that this effect is dependent on fasting-mediated reduction in insulin, IGF1 and leptin." (PMID 37907500, 2023).
cancer (continued). "In the case-control study, GH (1.80 vs. 0.90 ng/ml, p = 0.018) and IGF-1 (ULN: 1.27 vs. 0.91, p = 0.003) at the last visit were higher in patients with post-diagnostic cancers, with a lower disease-controlled rate." (PMID 37442901, 2023). "Ginsenoside F1 enhances natural killer (NK) cell cytotoxicity in cancer immunosurveillance by insulin-like growth factor-1 (IGF-1) treatment." (PMID 36771109, 2023). "IGF‐1, as a growth hormone, is conventionally known to stimulate cancer cell proliferation and tumor growth." (PMID 37849438, 2023). "In this way, the current evidence-based review serves as a complete reference for all kinds of phytochemicals that promote ROS-associated apoptosis via targeting various signaling molecules, including IGF-1 in cancer cells." (PMID 37560308, 2023). "Previous studies have shown that the AKT/GSK3β/c-Fos/NFATc1, IGF-1/AKT/NF-κB (RelA) or TGF-β/Smad3/4 signaling cascade play a key regulatory role in BMM of many cancers." (PMID 37337244, 2023). "Differences in hormonal levels of estrogen and insulin, growth factors such as IGF-1, and inflammatory mediators have been proposed as possible explanations for these differences in esophageal and other cancer incidence and survival." (PMID 36900690, 2023). "This review will summarize the contribution of IGF-1 signaling to the development of PCa and highlight the relevance of this signaling axis in potential strategies for cancer therapy." (PMID 36831629, 2023). "Of the 6141 total patients treated with IGF-1/R inhibitors, 2825 received monotherapy, 3315 received combination therapy, 5951 were treated for cancer, 161 were treated for TED, and 28 were healthy." (PMID 37240591, 2023). "IGF1 signaling is an important survival signal for cancer cells as the activator of phosphatidylinositol-3 kinase(PI3K)/Akt signaling." (PMID 36774408, 2023). "Differences in circulating IGF-1 and its inhibitors (IGFBP-2 and IGFBP-3) have been associated with the risk of several cancers, thus proposing these indicators as non-invasive biomarkers for cancer risk and prognosis." (PMID 38137390, 2023). "Our results also showed that low levels of IGF1 induce the expression of miR-15b in M6 cells (carcinoma), and miR-15b inhibition induced the expression of Igf1r, suggesting a possible feedback loop between IGF1/IGF1R and miR-15b." (PMID 37686596, 2023). "Animal studies confirmed that IGF-1 administration increased the cancer cells proliferation and their capacity to spread in secondary sites." (PMID 35222270, 2022). "Cancer-associated fibroblasts (CAF), too, express Igf1 RNA in tumors collected from a mouse model of invasive lobular carcinoma." (PMID 36556357, 2022). "Insulin-like growth factor-1 (IGF-1) pathway has been suggested to be associated with canceration and cancer progression." (PMID 35255873, 2022). "In conclusion, we have identified a set of small molecules that reduces both endo- and autocrine activities of the GH/IGF1 axis with the potential to inhibit GH-driven cancer growth and anti-cancer drug resistance." (PMID 35966052, 2022). "Next, we assessed aberrant AR, IGF1, and Wnt/β-catenin signaling pathways in both human primary PCa samples from the TCGA Pan-Cancer Atlas and advanced PCa samples in cBioPortal33,34." (PMID 35902588, 2022). "Over a long period, insulin has been regarded as a compensatory hormone of IGF-1 in cancer development and progression." (PMID 35252207, 2022). "Laboratory studies revealed that, under an IGF-1 inhibited environment, insulin works as the backup line for cancer cells to gain chemoresistance and resist IGFR related therapies in PDA cells." (PMID 35252207, 2022). "Cancer-associated proteins, such as MYC, IGF-1, and MMP9 were identified as the main hubs in the resulting networks, and it had been previously reported that they were related to tumorigenesis and metastasis." (PMID 35711939, 2022).
cancer (continued). "A growing number of studies indicate the involvement of autocrine GH and IGF1 in tumor growth promotion, and demonstrate that effective therapeutic options for cancer treatment need to drastically lower serum IGF1, reviewed in:." (PMID 35966052, 2022). "Further, both GH and IGF-1 appear to contribute to the development, progression, therapy resistance and metastases of multiple human cancers expressing GHRs." (PMID 35665221, 2022). "This association of growth hormone (GH)/insulin-like growth factor 1 (IGF-1) axis and cancer risk is complex." (PMID 37435457, 2022). "FAK activation-mediated nuclear translocation of Yes-associated protein (YAP) is also characterized in insulin-like growth factor-1 (IGF-1), and its cognate receptor engaged proliferation in cancer cells." (PMID 35163650, 2022). "Following our analysis of cancer hallmarks from the perspective of the IGF1 signaling pathway, it is relevant to question what was the rationale behind the identification of IGF1R as a therapeutic target." (PMID 36479090, 2022). "We review and discuss recent data supporting a key role for IGF-1 in tumor microenvironment-mediated tumorigenesis and cancer drug resistance development." (PMID 36017326, 2022). "So, it is believed that the application of QFG in the therapy of cancers would provide benefits in these aspects by the regulation of IGF1." (PMID 35280511, 2022). "A ketogenic diet targets glucose metabolism in cancer cells, inhibits the IGF-1 and PI3K/AKT/mTOR pathways, and suppresses CC, muscular wasting, and tiredness." (PMID 35565236, 2022). "In cancer, extracellular IGF-1 stimulates cancer cell proliferation, survival, cell migration, stem cell-like features, and epithelial to mesenchymal transition (EMT)." (PMID 36465383, 2022). "Further IPA pathway analyses indicated that multiple cancer-associated pathways, such as transforming growth factor-β (TGF-β), mTOR, IGF-1, nuclear factor-κB (NF-κB) and phosphatase and tensin homolog (PTEN) pathways, were correlated with CPSF6 expression." (PMID 36446361, 2022). "IGF1 stimulates a mitogenic response in primary cultures of cells from various origins as well as in cancer cell lines." (PMID 36479090, 2022). "miR-29b can promote different types of muscle atrophy induced by denervation, Dex, fasting, aging, and cancer cachexia by targeting IGF-1 and PI3K (p85a)." (PMID 35204692, 2022). "Taken together, these observations support that IGF-1 is a key player in tumor microenvironment-mediated tumorigenesis, metastasis, and anti-cancer drug resistance." (PMID 36017326, 2022). "Many epidemiological studies have reported that circulating IGF-1 is positively correlated with various primary cancers such as those of the breast, colon, and prostate." (PMID 35203722, 2022). "IGF-1 is known for its role to support cancer progression and metastasis through the promotion of neovascularization in transforming tissues, and the promotion of the proliferation, maintenance and migration of malignant cells." (PMID 36017326, 2022). "In PDAC, CAFs stimulate the invasion activity of cancer cells via paracrine IGF1/IGF1R signaling, especially under hypoxia." (PMID 35488263, 2022). "Increased levels of insulin and IGF-1 can would promote tumors growth and progression by binding to the overexpressed insulin receptor in many cancers." (PMID 35463353, 2022). "Klotho can suppress cancer by inhibiting IGF-1 signaling, which is known to be upregulated in cancer cells and promotes cancer growth and metastasis." (PMID 35666743, 2022). "Oncogenes and growth factors can promote cell proliferation, among which IGF-1 and c-Myc are used as targeted factors for cancer treatment." (PMID 35681494, 2022). "IGF-1 is not only involved in the regulation of obesity, cancer, metabolism, and aging, but also affects the survival and maturation of cells." (PMID 35203722, 2022).